CD4 (CD4 molecule)
Diseases named in the same sentence as CD4 in open-access papers (continued):
Sharing a sentence is not in itself a finding about the gene and the disease.
infection (continued). "Neutralizing antibodies against SARS-CoV-2, along with the creation of memory B cells and CD4+ and CD8+memory T cells, which are generated by infection, vaccination, or after reexposure, are key to the path to immunity." (PMID 35632490, 2022). "This is crucial as IFN-γ production by CD4 T cells stimulates keratinocytes to secrete CXCL9 and CXCL10, which then recruit CD8 T cells to sites of infection." (PMID 36211447, 2022). "To avoid potential variation, we conducted a 1:1 case–control study based on PSM analysis to adjust the factors of age, baseline CD4+ T-cell count, baseline HIV-1 RNA level, gender, mode of infection, marital status, cART regimen and cART adherence." (PMID 36483196, 2022). "Our results demonstrate that SARS-CoV-2 reactive CD4+ and CD8+ T cells recognize alpha, delta and omicron VOC 11 months after infection in vaccinated adults with equal avidity." (PMID 36389833, 2022). "Since HCQ is continuously released to maintain T cell immune quiescence, it is assumed that this will provide sufficient time for the SLNs to be released, enter CD4+ T cells and silence CCR5 gene expression to prevent infection." (PMID 33866528, 2022). "Here, we reveal the presence of a TCRαβ+CD8α-NK1.1-CD4+GzB+ T cell population, which represents around 30% of the CD4+ T cells in the spleen of C57BL/6 (B6) mice, in the acute phase of infection with T. cruzi." (PMID 35670567, 2022). "These alterations in the kinetics of monocytes, neutrophils, and CD4+ T cells coincided with a significant increase in serum concentration of TNFα, IFNγ, CXCL10, and IL-10 early after infection." (PMID 36466866, 2022). "CD4 + and CD8 + T cells proliferation assessment in mice infected with ZIKV induced a strong adaptive immune response, which helped prevent infection in the brain and testes." (PMID 34997041, 2022). "The RPs is defined as an infection that appears within 3 years; TPs as an infection that appears between 8 years to 10 years after the first infection; LTNP is defined based on the number of CD4 cells > 400 after infection over 10 years." (PMID 36032099, 2022). "Of note, the phenotype and functionality of vaccine-induced CD4+ and CD8+ T cells also resembled those after natural infection." (PMID 36318037, 2022). "In swine infected by PRRSV, cell-mediated immune (CMI) responses are characterized by cytokine secreting cells (SC), mainly IFN-γ-secreting, CD8+ and CD4+/CD8+ double-positive T cells, detectable 2–3 weeks post-infection and showing an erratic behavior." (PMID 35215119, 2022). "Latently infected CD4+ T cells were most abundant during acute SIV (~8% of memory CD4+ T cells) and persisted in chronic and cART-suppressed infection." (PMID 35510859, 2022). "In primary infections, the CD103+ cDC1 subset is crucial for efficient processing and presentation of viral antigens to both naïve CD8+ and CD4+ T cells in these LNs." (PMID 36895258, 2022). "We have previously shown that acute NrHV infection in C57BL/6 mice is associated with the hepatic infiltration of lymphocyte subsets and CD4+ and CD8+ T cell dependent clearance 21-28 days post infection (pi)." (PMID 36159876, 2022). "SIVkrc infection has been characterized by downregulation of SLAMF6 and CD4, immune genes undergoing downregulation in HIV infection, and upregulation of the immunosuppressive gene CD101 during infection." (PMID 36713371, 2022). "As shown in a previous study, Sendai virus-specific CD4+ TRM persists in lung tissues and the airway for several months after infection in C57BL/6 mice, mediating a substantial degree of protection against secondary virus infection." (PMID 35055244, 2022). "This efficient viral function of the HIV-1 Env, in a CD4 dependent manner, allows the virus to overcome cell barriers that limit HIV-1 Env-mediated pore fusion formation, viral entry to the cell, infection and replication." (PMID 36140273, 2022).
infection (continued). "The DC uptake model indicates strong compartmentalisation of CD4 and CD8 processing and peptide display and indicates that a combination of uptake and direct infection is likely to be most effective in vaccine generation." (PMID 35051231, 2022). "There is evidence that cellular immune responses that include the early development of HCMV-specific CD4+ and CD8+ T cells can contribute to reducing the transmission of the virus from pregnant women to the fetus after primary infection in the first trimester." (PMID 35891239, 2022). "SPexp mice, as expected, had increased frequencies of circulating Ag-experienced CD4 and CD8 T cells 5 d after the last infection." (PMID 35878936, 2022). "CD4+T cells often coproduce IL-10 and IFN-γ, designated type 1 regulatory T cells (Tr1s), and promote the onset of infection by suppressing Th1 cell-mediated immunity." (PMID 35585983, 2022). "The results of the current study indicated a significant reduction in the levels of CD3+, CD4+, and CD8+ T cells in the moderate infection and under-medication groups compared to the healthy group." (PMID 35196808, 2022). "Our results suggest that CoronaVac promotes CD4+ T cell responses against SARS-CoV-2, which can be protective against infection and/or severe disease." (PMID 36383021, 2022). "CD4+ and CD8+ tissue resident memory (Trm) cells are present at barrier sites and provide a rapid response to infection." (PMID 36159872, 2022). "Two individuals may have similar early CD4 counts but may still have been infected by T/F strains of different fitness if their pre-infection CD4 counts were different, with the individual with the higher pre-infection count infected by the more virulent T/F strain." (PMID 35271687, 2022). "Compared to unexposed individuals, convalescent patients exhibited greater CD4+ T cell reactivity toward peptide pools derived from the SARS-CoV-2 structural proteins S, M and N at approximately 3 months post infection." (PMID 35514974, 2022). "Among CD4+CD8 pool responders, the frequency of positive IFN-γ in matched asymptomatic and symptomatic post-infection to S, N, and M pools were compared." (PMID 35390102, 2022). "In particular, the wrong classification of long-term infections as recent increases in HIV-infected people with low CD4 T-cell counts or in HIV-infected people on antiretrovirals, including those who started ART soon after their infection." (PMID 36359500, 2022). "Regarding the CTLA-4+PD-1+ DP phenotype, there were less than 5% of effector CD4+ or CD8+ T lymphocytes in the infected group, the most expanded population after infection." (PMID 35720410, 2022). "MDV establishes a latent state by approximately 21 days post-infection, during which the MDV genome can be detected integrated into the chromosomes of transformed CD4+ CD25+ T cells." (PMID 35056456, 2021). "During B cell infection, EBV upregulates CD4 on already CXCR4-expressing cells, and X4 tropic HIV strains can establish infection as well as reversely transcribed viral DNA integration in EBV-transformed B cells." (PMID 34778072, 2021). "Here, we report SARS-CoV-2 specific T cell responses in infected adults and children and find that the acute and memory CD4+ T cell responses to structural SARS-CoV-2 proteins increase with age, whereas CD8+ T cell responses increase with time post-infection." (PMID 34326343, 2021). "We found significant infiltration of IL-17-secreting CD4+ tissue-resident memory T (TRM) cells and Siglec-F+ neutrophils into the nasal tissue during primary infection with B. pertussis." (PMID 33976385, 2021). "The proportion and the absolute number of activated CD4+ CD44hiCD62Llo cells that also expressed IL-4 peaked in the BALF, lung digest, and draining lymph nodes (TBLN) of adults at day 11 post-infection and in neonates at day 28 or later post-infection." (PMID 34682248, 2021).
infection (continued). "We used a novel, age-stratified, CD4-staged Bayesian back-calculation model to estimate HIV incidence and undiagnosed infections among adult MSM (age ≥15 years) during the 10-year period between 2009 and 2018." (PMID 34118196, 2021). "Nef induces TCR-independent activation of T cells and allows for the infection of neighboring T cells through the CCR5 and CXCR4 receptors, contributing to bystander-induced apoptosis and depletion of CD4+ T cells." (PMID 33467074, 2021). "At day 8 after infection, we found that the frequencies and numbers of total and effector (CD44+ CD62L-) CD4+ T cells derived from Ddb1-TaKO (CD45.1+ CD45.2+) BM was much lower compared with that derived from WT (CD45.2+) BM." (PMID 34526995, 2021). "We observed more CD4+ T helper cells and CD8+ cytotoxic T cells in lungs of Lcn2-/- mice seven, nine and 16 days after infection." (PMID 33905460, 2021). "The 32-degree- and 37-degree-infection groups had higher proportions of naive T cells, in terms of both CD8-positive T cells or CD4-positive cells, than the other infection groups." (PMID 33953713, 2021). "The existence of CD8+ cytotoxic T lymphocytes (CTL) signifies an essential relationship for reducing infection and resembles a decrease in clinical signs by the action of major histocompatibility complex (MHC), and lysis is facilitated by CD8+CD4 cells." (PMID 34822646, 2021). "With respect to the four main thymocyte populations, DP, CD4 single positive (SP) and CD8SP are the ones most affected after infection, in an IFNγ and NO independent manner." (PMID 34987496, 2021). "To achieve this, we isolated CD4+ T cells, then pre-incubated activated CD4+ T cells with pEVs from HCs, HIV infected on ART or ART-naïve individuals before infection with the CXCR4-tropic HIV LAI virus." (PMID 34249000, 2021). "Although the levels of nAb following natural infection or vaccination influence the outcome of reexposure or infection, SARS-CoV-2-specific CD4+ and CD8+T cell responses are also relevant to the protection." (PMID 34712742, 2021). "Conditioned CD4+ T cells were then exposed to HIVGFP, and assessed 3 days later for infection rates." (PMID 33976386, 2021). "We therefore infected primary CD4+ T cells with HIV-1 and assessed genome-wide RNA expression at 4.5, 8, 12, 24, and 48 h following infection." (PMID 34154423, 2021). "After 30 days of infection, CXCR3+CCR5+CCR4+ CD8+ T-cells were predominant in the blood (Student’s t-test, p = 0.001), as reported for CD4+ T-cells." (PMID 34685494, 2021). "Our results revealed that PEDV replicated in BM-DCs and that PEDV infection of cells inhibited expression of swine leukocyte antigen II DR (SLA-DR), a key MHC-II molecule involved in antigen presentation and initiation of CD4+ T cell activation." (PMID 34858400, 2021). "On the one hand, CD4+ T cells have been proved to be important mediators of protection against ZIKV, in several infection and vaccination context." (PMID 34213405, 2021). "Three factors (infection, SNP, heavy metals) having etiological roles in the development of the autistic pathology were compared to the number of helper T-cells (CD3+/CD4+)." (PMID 35002805, 2021). "During HIV infection, CD4+ T-cells are depleted, which suggests that finding and recruiting enough CD4+ T-cells to specifically target HBV to prevent subsequent infection represents an onerous task for the immune system." (PMID 35069530, 2021). "Except for 6 weeks after infection, part of the specific TIGIT+CD4+ T cells of T. gondii in the spleen of the PRU group were activated and transformed into TEM." (PMID 34421855, 2021). "It has been shown that total HIV- DNA load during ART reflects pre-ART characteristics of infection, such as baseline HIV- DNA load, pre-ART HIV-RNA load and the CD4+ cell count nadir." (PMID 35054206, 2021). "A separate cell-to-cell infection assay was performed to measure productive infection between HIV-expressing Jurkat cells and primary CD4 T cells." (PMID 35062242, 2021).
infection (continued). "However, the spike-specific CD4+ T cells from the convalescent and infection-naïve individuals exhibited clear phenotypic differences when assessed by both MDS and tSNE contours; this was more apparent after the second vaccine dose, but could already be observed after the first." (PMID 34636722, 2021). "As with the gamma response, the Mtb-specific CD4+TNF- α+T cells and CD8+ TNF-α+T cells elicited by Mtb CW stimulation at 3 weeks post-infection was significantly higher in the high dose group compared to the low dose group." (PMID 34484203, 2021). "At 7 and 10 days after infection, lung and mediastinal lymph nodes (MLN) cells were collected to determine the numbers of total CD4 + and CD8 + T cells, and IAV-specific CD4 + and CD8 + T cells, using flow cytometry." (PMID 33879121, 2021). "A significant increase in CD4 and CD8 T cells were observed at 7 and 3 days post-NNV infection, respectively." (PMID 33467734, 2021). "After infection with Mtb, these mice exhibit increased levels of the pro-inflammatory cytokines TNF and IL-12 followed by an enhanced activation of CD4+ T cells in the lung, which eventually culminates in reduced bacterial burdens." (PMID 35116036, 2021). "Strikingly, infection with S. tm. induced in eSPF+SFB mice compared to SPF mice significantly increases the frequencies and numbers of IL-17A-IL-22+ and IL-17A+IL-22+ CD4+ T cells specifically in the cecal LPLs." (PMID 34566952, 2021). "Strains that are exclusively R5 predominantly infect monocyte-derived macrophages and memory CD4 cells, which are the prime targets of HIV-1 early in infection, while exclusively X4 strains predominate at a later stage and prefer naïve and resting T cells." (PMID 35126374, 2021). "At days 2, 3, and 8 after infection, we analyzed frequency and cell number of the donor SMARTA CD4+ T cells by flow cytometry." (PMID 34526995, 2021). "To investigate the specific role of T cells in recovery from SARS-CoV-2 infections we studied rhesus macaques that were depleted of either CD4+, CD8+ or both T cell subsets prior to infection." (PMID 33821272, 2021). "Upon PbA-infection the proportion of CCL5+ monocytes vanished, so that CD8+ T cells (17.8%), CD4+ T cells (16.8%) and eosinophils (16.7%), together with M2-like macrophages (9.2%) were the main CCL5 producers in spleens of PbA-infected Ifnar1-/- mice." (PMID 34659202, 2021). "The CD69+CD103+ CD4+ and CD8+ T cells were maintained in the tissue during FTY720 treatment and proliferated during the course of infection." (PMID 34564636, 2021). "We investigated the relative abundances of key immune cells, including CD4 T cells, CD8 T cells and B cell lymphocytes in the lungs of mice on day 7 post infection." (PMID 34452495, 2021). "The frequency of CD4, CD8, and γδ T cells remains relatively stable throughout the course of infection, or at least through the time points analyzed in this study (4, 8, and 48 weeks post-infection)." (PMID 34336973, 2021). "Therefore, HIV-1 containing PSGL-1 might infect CD4+ T cells via trans-infection." (PMID 34696365, 2021). "In the chronic phase of the infection, a continued IFN-α2a treatment in the course of intrarectal SIV infection accelerated CD4+ T cell depletion, disease progression, and death from AIDS, suggesting a detrimental effect of IFN-I as the disease progresses." (PMID 34512664, 2021). "Over the past ten years, the protective capabilities of CD4+ and CD8+ TRM cells have been demonstrated for members of all pathogen classes, including fungi, predominantly in murine infection models." (PMID 34113356, 2021). "CD4+ and CD8+ T cells serve a prominent role against infection with mucormycosis via recruiting cytokines, such as IL-4, IL-10, IL-17, and IFN-γ5." (PMID 34036149, 2021). "In contrast, SHIVSF162P3CN infection resulted in strong anamnestic CD8+ and CD4+ T cell responses against Gag-p27 in pRhPD1-p27-immunised macaques." (PMID 34125864, 2021).
infection (continued). "Benzyl-derivatized peptides corresponding to residues 81–92 of CD4 inhibit HIV-1-induced cell–cell fusion and infection at micromolar concentrations." (PMID 34959554, 2021). "In the CD4+ T-cell compartment, recently activated CD279 (PD-1)+ cells as well as those with TEM and TCM phenotypes were affected by rDEN2Δ30 infection." (PMID 34031380, 2021). "In the acute phase of infection, IFN-γ and IL-12, which involve CD8+ T cells, play critical roles in the detection and elimination of pathogens and, to a lesser extent, CD4+ T cells." (PMID 33748214, 2021). "We focused on the similarities and differences in the activated gene pathways between CD4+ and CD8+ T cells during early infection." (PMID 34603402, 2021). "In mice it was shown that migrating and resident memory T cells intersperse to establish long-term memory against HSV-1; however, key differences in the localisation of memory CD4+ and CD8+ T cells occurred following infection." (PMID 33668777, 2021). "Previous studies also reported an increase in the percentages of CD4+ and CD8+ T cells in blood and lymph nodes after Neospora experimental infection in cattle." (PMID 34239816, 2021). "The CD32+CD4+ T cell profiles in SLT and gut upon SIVagm infection suggest such a direct effect of the virus." (PMID 34220857, 2021). "The expression of TIM-3 can occur jointly with the expression of other makers, in particular with PD-1 (i.e., TIM-3+ PD-1+ CD4+ and CD8+ T cells), in the late stages of infection." (PMID 34946062, 2021). "Histochemistry and flow cytometry confirmed an increasingly higher number of infiltrated macrophages, neutrophils and CD4+ and CD8+ T lymphocytes upon infection." (PMID 34525131, 2021). "The modules that were co-up-regulated in CD4 and CD8 cells after infection included IRF9, IRF7, PLCB3, CXCL3, and TXN, among others." (PMID 34603402, 2021). "Because Baft3 dependent DCs represent an important source of IL-12 in the skin, they likely impact Th1 CD4+ cells and CD8+ T cells activation at the site of infection despite their low numbers." (PMID 34557194, 2021). "Levels of specific lymphocyte subsets and immunoglobulins, such as CD3+CD4+ T cells, CD3+CD8+ T cells, and immunoglobulin G, are reported to be related to infection in chronic autoimmune diseases." (PMID 34122322, 2021). "CD4+ T cells differentiate into TH1 cells that produce IFNγ and TNFα in the infection with rickettsiae and orientiae." (PMID 34452021, 2021). "This proof-of-concept study was focused on the immune control of bacillary burden after infection, as our recent NHP work demonstrated that this CD4+ T-cell subset is required to control very early Mtb dissemination." (PMID 33732233, 2021). "Following P. murina infection, infiltration of activated CD4+ and CD8+ T cells into the lung parenchyma and BALF was higher in Lyz-Arg−/− neonates at day 30 post-infection compared to wild type pups." (PMID 34682248, 2021). "The proportion of TH2 (CD4+ CD44+ FoxP3- Tbet- GATA3+) cells was significantly lower than the TH1 cells, and ranged from 4% - 11% of the activated CD4+ T-cells in the UgCl223 infection." (PMID 35186781, 2021). "Cd4-cre+Egr2f/f mice (cKO), or Cd4-cre+Egr2+/+ littermates (WT), were infected with LCMV-Cl13 and the response to infection was assessed." (PMID 33986293, 2021). "Furthermore, CD4+ T cells activated within PBMCs display a more activated phenotype with high expression levels of the cellular activation markers CD25, CD69, CD38, and immune checkpoint molecule protein death 1 (PD-1), and are significantly more susceptible to infection by CCR5-tropic HIV." (PMID 34899645, 2021). "The analysis of HIV-1 spreading infection in CD4+ T-cells and LVL PBMCs co-cultures at all CD4:PBMC ratios demonstrated marked inhibition of HIV-1 replication in cultures with matching HLAs compared to CD4+ T-cells alone." (PMID 34122382, 2021).